DLK1 (delta like non-canonical Notch ligand 1)
Diseases named in the same sentence as DLK1 in open-access papers (continued):
Sharing a sentence is not in itself a finding about the gene and the disease.
breast cancer (10 papers, 2005 to 2025). A primary or metastatic malignant neoplasm involving the breast. "DLK1’s different expression levels have been shown to inversely modulate the oncogenic potential of breast cancer cells through inhibition of NOTCH1 signaling." (PMID 41139924, 2025). "In a previous work, we studied the role of DLK1 in the tumor properties of MDA-MB-231 breast cancer cells." (PMID 35163478, 2022). "Until recently, Nueda and co-workers discovered that high and low levels of DLK1 inversely affect breast cancer proliferation, adding to the complexity." (PMID 31661545, 2019). "As Dlk1 mRNA levels were unaffected (not shown), we directly assessed the levels of active Notch and its downstream target Hey1 in mammary tumors derived from wild-type and Postn-deficient animals." (PMID 25592291, 2015). "In the HER2-negative breast cancer cohort treated with Bevacizumab, MMP2, COL5A2, COL6A1, DLK1, and MDK were identified as predictive of treatment response, aligning with their documented roles in angiogenesis and stromal interactions." (PMID 41139924, 2025). "We also analyzed the effects of different levels of DLK2 expression on other signaling pathways already known to be affected by DLK1 expression and NOTCH signaling, which ultimately affect gene expression and cell behavior in breast cancer cells." (PMID 35163478, 2022). "Most likely, the level of NOTCH activation, modulated by DLK1 and DLK2, may led to opposite effects on the invasive properties of MDA-MB-231 breast cancer cells and tumor cell growth in vitro and in vivo." (PMID 35163478, 2022). "In contrast, ATP7A, DLK1, CRBP1, and SMAD3 were not modulated by aRA in RA-sensitive lung and breast cancer cells." (PMID 16012519, 2005). "Finally, the PI3K/AKT pathway, an important signaling pathway related to cell quiescence and proliferation, which is activated in 30–40% of breast cancer cases, was not modified in MDA-MB-231 cells transfected with DLK1." (PMID 35163478, 2022).
Glucose intolerance (10 papers, 2014 to 2022). Glucose intolerance (GI) can be defined as dysglycemia that comprises both prediabetes and diabetes. "Ectopic overexpression of DLK1 resulted in a lipodystrophic phenotype related to triglyceride accumulation and glucose intolerance." (PMID 34527673, 2021). "For example, over expression of miR-127, a Dlk1-Dio3 mat NAFLD candidate, in pancreas islet cells suppresses insulin secretion and causes glucose intolerance; additionally, miR-342 and miR-379 are upregulated in white adipose tissue of obese mice." (PMID 27135827, 2016). "Interestingly, a previous study showed that exogenous uptaken of DLK1 attenuated hepatic steatosis, hyperglycemia and glucose intolerance in the diabetic mice." (PMID 34527673, 2021).
hepatoblastoma (8 papers, 2015 to 2025). Hepatoblastoma (HB) is a malignant hepatic tumor and is the most common pediatric liver cancer. "Single cell sequencing of fetal liver affirmed DLK1 as another marker of the KRT19highCD326high hepatoblastoma phenocopy with potential clinical relevance." (PMID 36845728, 2023). "Then we specifically investigated the individual genes that indicate hepatocyte differentiation (Cyp2e1), hepatoblastoma markers (Igf2, Afp, Glul, Krt19) and embryonal hepatoblastoma stem cell markers (Dlk1, Epcam and Gpc3)." (PMID 37414763, 2023). "HUH6 and HepG2 cells exhibited stronger transcriptomic activation of AFP, DUSP9, GPC3, DLK1, MYC compared to other non‐hepatoblastoma cell lines." (PMID 40271711, 2025). "Meanwhile, other known markers of hepatoblastoma, including AFP, DLK1, and GPC3, were upregulated in the epithelial (similarly in both fetal and embryonal) but not mesenchymal components." (PMID 39567523, 2024). "All tumoroids at early passage showed expression of known hepatoblastoma markers, AFP, DLK1, and the Wnt target gene, AXIN2." (PMID 39567523, 2024). "We first performed a transcriptomic evaluation of the two well‐recognized hepatoblastoma cell lines, HepG2 and HUH6, using Pearson's analysis with gene signatures in the public GSE168997 dataset to elucidate IGF2′′s role in hepatoblastoma (AFP, DUSP9, GPC3, DLK1, MYC, EPCAM, KRT8, and LIN28B)." (PMID 40271711, 2025). "Clusters 0, 2, and 4, characterized by high expression of known hepatoblastoma markers, including AFP, DLK1, and GPC3, were shared among all the tumoroids, while the remaining clusters of cells were more heterogeneously represented across the different tumoroids." (PMID 39567523, 2024).
Hyperglycemia (8 papers, 2014 to 2024). An increased concentration of glucose in the blood. "Intrauterine hyperglycemia alters imprinted genes, and could cause abnormal Dlk1 and Gtl2 expression related to dysregulation of Dlk1-Gtl2 methylation in placenta of both F1 and F2 offspring." (PMID 29854287, 2018). "Furthermore, it is put forward that intrauterine hyperglycemia leads to abnormal placental DLK1 expression due to DNA methylation among next-generation mice." (PMID 34540403, 2021).
neuroendocrine tumors (8 papers, 2006 to 2026). "Our data support the clinical testing of targeting DLK1 with an ADC in ACC and other neuroendocrine neoplasms and identify DLK1 as an important cell surface target for future immunotherapeutic approaches." (PMID 39416174, 2024). "Dlk1, a member of the Epidermal Growth Factor family, is expressed in multiple tissues during development, and has been detected in carcinomas and neuroendocrine tumors." (PMID 23577150, 2013). "There is evidence that Dlk1 is a growth regulator, and the Dlk1 transcript is overexpressed in many human neuroendocrine tumors." (PMID 17014736, 2006). "Therefore, the authors suggested that DLK1 might be involved in neuroendocrine differentiation, and could be a potential therapeutic target in neuroendocrine tumors." (PMID 33435319, 2021). "Furthermore, Dlk1 has been observed in various carcinomas including neuroendocrine tumors." (PMID 23577150, 2013). "This work identifies DLK1 as an immunotherapeutic target that regulates tumor cell plasticity and chemoresistance in ACC and supports an active phase I clinical trial targeting DLK1 with an ADC in ACC and neuroendocrine neoplasms (NCT06041516)." (PMID 40595495, 2025). "We observed high DLK1 expression in a subset of refractory cancers such as sarcomas, SCLC, germ cell tumors, and grade 2 neuroendocrine tumors." (PMID 39416174, 2024). "Our data support targeting DLK1 with an ADC in ACC and neuroendocrine neoplasms in an active first-in-human phase I clinical trial (NCT06041516)." (PMID 39416174, 2024). "In summary, we have identified DLK1 as a new immunotherapeutic target in ACC and neuroendocrine neoplasms such as SCLC." (PMID 39416174, 2024).
non-small cell lung carcinoma (8 papers, 2010 to 2024). A group of at least three distinct histological types of lung cancer, including non-small cell squamous cell carcinoma, adenocarcinoma, and large cell carcinoma. "An association between DLK1 expression and patient prognosis was reported in small cell lung cancer, non-small cell lung cancer, ovarian cancer, and gastrointestinal stromal tumor." (PMID 39769389, 2024). "Upregulated expression of DLK1 in non-small cell lung cancer is associated with lymph node metastasis, but the mechanism is still unknown." (PMID 24621612, 2014). "We found that TRIM67 altered the behaviour of non-small cell lung cancer (NSCLC) cells by ubiquitinating DLK1 via its RING domain, which in turn activates the Notch pathway." (PMID 38434968, 2024). "Methylation of the DLK1 gene promoter region increased the invasive ability of non-small cell lung cancer cells." (PMID 32349667, 2020). "Nevertheless, we observed positive staining of DLK1 in cancer cell nuclear during immunohistochemistry (IHC) experiments on non-small cell lung cancer (NSCLC) tissues." (PMID 31661545, 2019). "Our previous work also found that DLK1 is highly expressed in human non-small cell lung cancer and functions as an oncogene." (PMID 24621612, 2014). "It has also been reported that DLK1 is aberrantly expressed in various types of human cancers, including non-small cell lung cancer." (PMID 24621612, 2014).
myelodysplastic syndrome (7 papers, 2005 to 2025). A clonal hematopoietic disorder characterized by dysplasia and ineffective hematopoiesis in one or more of the hematopoietic cell lines. "Also, the mRNA expression of DLK1 that has been implicated in myelodysplastic syndrome and the Polycomb repressive complex 2 (PRC2) member JARID2 were potentially de-regulated by nearby putative enhancers." (PMID 37495775, 2023). "The precise function of the DLK1 protein is unclear, but DLK1 expression is upregulated in myelodysplastic syndrome, a slowly progressing haematological malignancy, and in uterine leiomyomata (compared to normal myometrium)." (PMID 15798773, 2005). "This study aims to investigate the expression of delta-like 1 (DLK1) gene in the bone marrow cells of patients with myelodysplastic syndromes (MDS) and to explore its molecular characteristics for the early diagnosis of MDS." (PMID 23691477, 2012). "Dlk1 encodes a non-canonical Notch ligand which has been reported to be overexpressed in human hematopoietic CD34+ stem and progenitors from myelodysplastic syndrome patients." (PMID 37353813, 2023). "DLK1 expression is elevated in the CD34+ cells and MNCs of myelodysplastic syndrome (MDS) patients and MNCs of AML patients, and increased levels of DLK1 are found in MDS patient sera." (PMID 30876483, 2019).
liver disease (6 papers, 2015 to 2022). "In summary, there are compelling data strongly suggesting that dysregulation of the PTTG1/DLK1 axis is involved in the pathogenesis of fat metabolism in liver diseases." (PMID 35805898, 2022). "An increased concentration of this biomarker in blood serum is associated with hepatic cancer whereas downregulation of DLK1 expression through an epigenetic mechanism contributes to attenuate liver disease." (PMID 27526683, 2016). "The expression patterns of Dlk1-Dio3 mat candidate miRNAs in human serum samples differed from the patterns in the mouse models of liver disease." (PMID 27135827, 2016). "The present article intends to extensively review the major mechanisms regulating synthesis, secretion, and maturation of PTTG1 and DLK1, as well as the principal evidence pointing to these peptides as possible antifibrogenic targets for the treatment of advanced liver disease." (PMID 35805898, 2022). "Given this background, we aimed to explore the hypothesis that PTTG1/DLK1 signalling should play a central role in the activation of the fibrogenic process in liver disease." (PMID 35050550, 2022). "For all these reasons, PTTG1/DLK1 axis could be of major importance in the pathogenesis of liver diseases." (PMID 35805898, 2022). "Furthermore, serum concentration of DLK1 also depicted a direct relationship with the degree of portal hypertension in fibrotic/cirrhotic animals (r = 0.41, P < 0.05)." (PMID 35050550, 2022). "This investigation aimed to explore whether PTTG1/DLK1 signalling contributes to the activation of the fibroproliferative process in liver disease." (PMID 35050550, 2022). "Pttg1 gene silencing normalizes expression of Dlk1, arrests activation of HSC, diminishes expression of ECM‐related genes and finally decreases hepatic collagen deposition and reduces portal hypertension." (PMID 35050550, 2022). "Thus, our study indicated that Dlk1 isoforms were differentially expressed and played distinct roles during committed HSC differentiation, providing clues and evidence for optimizing cell therapy strategies for liver disease." (PMID 30646961, 2019). "Therefore, these intriguing results indicate that Dlk1 might be a regulator of HSC differentiation and liver development, providing clues and evidence for future clinical applications of cell replacement therapy for liver disease." (PMID 30646961, 2019).
ovarian carcinoma (6 papers, 2012 to 2025). A malignant neoplasm originating from the surface ovarian epithelium. "DlK1 are elevated in ovarian cancer and promotes tumorigenesis and epithelial-mesenchymal transition of high-grade ovarian carcinoma through activation of Notch signaling." (PMID 33968932, 2021). "TATs highly expressed in cervical cancer include CEACAM5, CD71, CD138, FGFR3, LYPD3, CEACAM6, etc.; VEGF is also highly expressed in ovarian cancer; CD71 and CD138 are highly expressed in endometrial cancer; the TATs highly expressed in uterine sarcoma include B7-H3, DLK1, and EFNA4." (PMID 40046734, 2025). "However, no study has focused on the relationship between Dlk1 methylation and ovarian cancer." (PMID 33282553, 2020).
renal cell carcinoma (6 papers, 2014 to 2024). "Overexpression of DLK1 has been found in pericytes within human renal cell carcinoma (RCC) biopsies or in murine models of renal carcinomas (RENCA)." (PMID 39086395, 2024). "Indeed, DLK1 is downregulated by epigenetic mechanisms in renal cell carcinoma." (PMID 25741387, 2014).
acute myeloid leukemia (5 papers, 2012 to 2024). Acute myeloid leukemia (AML) is a group of neoplasms arising from precursor cells committed to the myeloid cell-line differentiation. "Our enrichment analysis results support previous findings, showing that DLK1 and HPGDS were involved in acute myeloid leukemia." (PMID 38184718, 2024). "Accumulating evidence implicates the imprinted genes from this locus, DLK1 and MEG3, in the development and progression of acute myeloid leukemia (AML)." (PMID 30876483, 2019). "The expression of DLK1 mRNA in the bone marrow cells of cases with MDS, acute myeloid leukemia (AML), and normal control groups were measured by real-time polymerase chain reaction and were analyzed for clinical significance." (PMID 23691477, 2012).
adrenocortical carcinoma (5 papers, 2024 to 2026). "Moreover, we show that DLK1 is targetable by an ADC, particularly in the rare cancer adrenocortical carcinoma (ACC) in which DLK1 is highly expressed." (PMID 39416174, 2024).
gastric cancer (5 papers, 2011 to 2025). A primary or metastatic malignant neoplasm involving the stomach. "Comparing the metabolites of gastric cancer cells and the differentially expressed genes under M0 and M2 intervention conditions, it was found that compared with the M0 group, the metabolite interference group of gastric cancer cells significantly promoted the appearance of DLK1 in macrophages." (PMID 39991579, 2025). "We transfected with gastric cancer cell lines with miR-193a-3p and transfected supernatant was collected to co-culture with 3T3-L1, the adipogenesis specific genes C/EBPα, PPARγ and Perilipin-1 were evidently elevated, and DLK1 was down-regulated in mimic group." (PMID 35541892, 2022).
gestational diabetes mellitus (5 papers, 2021 to 2024). "In this analysis, we explored the hypothesis that paternally expressed DLK1 polymorphisms could affect maternal circulating DLK1 concentrations, and that this could affect maternal metabolism and risk of gestational diabetes mellitus (GDM)." (PMID 33640968, 2021). "We aimed to search serum DLK1 and nesfatin-1 concentrations at 24-28 weeks of pregnancy in women newly defined with gestational diabetes mellitus (GDM) and investigate the relationship of these adipokines with various metabolic parameters." (PMID 34540403, 2021).
glioblastoma (5 papers, 2020 to 2024). The most malignant astrocytic tumor (WHO grade IV). "To investigate if the Dlk1-Dio3 marker genes were associated with any cell states we utilized single cell RNA-seq data from 4 different studies, which included 50 glioblastomas (45 unique tumors) and 16,269 cells after filtering." (PMID 38609422, 2024). "An association between DLK1 expression and aggressive tumor growth in glioblastoma has previously been established." (PMID 33142235, 2020). "In this study, we highlight that miRNAs from the Dlk1-Dio3 and miR-224/452 clusters may be expressed cell autonomously and that their expression is associated with cell state genes in glioblastoma." (PMID 38609422, 2024). "The Dlk1-Dio3 and miR-224/452 clusters are associated with glioblastoma cell states." (PMID 38609422, 2024). "In this study we identified miRNAs from the Dlk1-Dio3 and miR-224/452 clusters which distinguished two subpopulations of cells in a primary glioblastoma culture and show that both miRNA clusters are associated with different glioblastoma cell states." (PMID 38609422, 2024). "In this study, we highlight miRNAs from the Dlk1-Dio3 and miR-224/452 clusters which may be expressed cell autonomously and have expression that is associated with cell state genes in glioblastoma, most prominently in neural progenitor-like and mesenchymal-like states respectively." (PMID 38609422, 2024). "Expression of the Dlk1-Dio3 and miR-224/452 clusters characterize subpopulations of a glioblastoma primary culture." (PMID 38609422, 2024). "Excluding genes which code for miRNAs or snoRNAs, these four were the most positively correlated across the glioblastoma tumors, indicating their expression corresponded well with Dlk1-Dio3 miRNA expression." (PMID 38609422, 2024). "We then treated the human glioblastoma cell lines with a recombinant protein corresponding to the DLK1 secreted part, and once again, the 2 DLK-responding cell lines showed significant increase in their proliferation." (PMID 33142235, 2020). "This increased HIF-2a expression was reflected in a stronger hypoxic response, as 2/3 human glioblastoma lines and PIGPCs displayed increased activation of HREs at 72 hours of culture in hypoxia with DLK1 stimulation, as measured in an HRE-luciferase assay." (PMID 33142235, 2020). "Furthermore, studies will need to be scaled up to include multiple tumors to determine if heterogenous expression of miRNAs from the Dlk1-Dio3 and miR-224/452 clusters are a common feature in glioblastoma or an isolated case." (PMID 38609422, 2024). "In conclusion, our study is the first to implicate the Dlk1-Dio3 and miR-224/452 miRNA clusters as potential regulators of glioblastoma intra-tumoral heterogeneity and may serve as valuable biomarkers for cell state identification." (PMID 38609422, 2024). "We cultured U3082MG and U3084MG human glioblastoma cells for 24 or 72 hours in 1% O2, stimulated or not with soluble DLK1." (PMID 33142235, 2020).
hyperlipidemia (5 papers, 2016 to 2025). "Dlk1 null mice display accelerated weight gain and hyperlipidemia and patients with DLK1 mutations show metabolic alterations in adulthood." (PMID 35295988, 2022). "Additionally, Dlk1-deficient mice exhibited accelerated adiposity and hyperlipidemia in adulthood." (PMID 39839367, 2025). "Four representational genes, including Apolipoprotein B gene (APOB), Carboxylesterase 1 gene (CES1), Delta Like Non-Canonical Notch Ligand 1 gene (DLK1), Lipase Maturation Factor 1, (LMF1), were contributed to hyperlipidemia." (PMID 27888796, 2016).